Y_RNA (Y RNA )
Gene: Miscellaneous RNA gene on chromosome 11 (129,030,459 to 129,030,572, forward strand). Ensembl gene ENSG00000206847.
Homologues: Orthologues: chimpanzee Y_RNA (99% identical), macaque Y_RNA (95% identical). Paralogues in human: RNY1P8 (82% identical), RNY1 (82% identical), Y_RNA (82% identical), Y_RNA (81% identical), RNY1P11 (80% identical), Y_RNA (80% identical), Y_RNA (79% identical), RNY1P10 (78% identical), Y_RNA (78% identical), Y_RNA (77% identical), RNY1P15 (76% identical), Y_RNA (76% identical), and 95 more.